ABCG1 (ATP binding cassette subfamily G member 1)
Diseases named in the same sentence as ABCG1 in open-access papers (continued):
Sharing a sentence is not in itself a finding about the gene and the disease.
tumor (continued). "Overall, these results indicate that fasting promotes cholesterol efflux via ABCG1 and possibly also via reduced ACAT1 expression, at least in some types of tumour cells." (PMID 37907500, 2023). "Correlation analysis of six prognostic MDGs (ABCG1, KDF1, KITLG, TGFA, HAVCR2, and CD14) and six types of immune infiltrating cells, including tumor purity, B cells, CD8+T cells, CD4+T cells, macrophages, neutrophils, and dendritic cells was performed." (PMID 35774505, 2022). "Four other ABC transporters showed this pattern, with elevation in the MDR tumor at least two-fold greater than in the control sample, and reduced by metformin (ABCA3, ABCC10, ABCG1, and ABCB3)." (PMID 36077749, 2022). "In addition, ABCG1 could affect tumor growth by regulating macrophages." (PMID 33825659, 2021). "We knocked out ABCG1 in AT2 cells, then cocultured with Lgr5 cells and found that the capacities of colony formation and tumor initiation of AT2 cells were suppressed." (PMID 32157214, 2020). "Furthermore, the anti-tumor effects observed were noted in relatively young (3-4 months) animals on regular chow diet and did not require either aged mice (6-7 months old) or a high fat “western”-type diet, as was recently reported as a requirement for tumor suppressive phenotype in Abcg1−/− mice." (PMID 29069761, 2017). "The inhibitory effect of cyAV3.3 on ABCG1 and KRAS in homospheroids might be due to the inhibitory effect of cell–cell interaction among tumor cells." (PMID 41584360, 2026). "In addition, some genes including ABCG1, KRAS, MMP2, MMP9 were inhibited by cyAV3.3 in homospheroids, which indicates the direct effect of ITGA5 inhibition on resistance in tumor cells." (PMID 41584360, 2026). "Indeed, cholesterol accumulation in tumor cells can activate LXRs, thereby promoting cholesterol efflux via ABCA1 and ABCG1." (PMID 39308527, 2024). "Since ABCG1 is detected to phosphorylate AKT, whether it also activates the other signal pathways to regulate more tumor types still need more investigations, but this kind of findings will shed a light on the novel function of ABCG1 in cancer development." (PMID 38896016, 2024). "HDL can alter the tumor microenvironment by modulating lipid content, especially by mediating excess cholesterol removal by ABCA-1, ATP-binding cassette transporter G-1 (ABCG-1), and scavenger receptor class B type 1 (SR-B1) through reverse cholesterol transport." (PMID 39195217, 2024). "In tumor, the absence of ABCG1 inhibits cancer cell growth through modulation of macrophage function as a mediator of tumor immunity." (PMID 38896016, 2024). "Abcg1 knockout mice were shown to suppress the growth of MB49 subcutaneous bladder carcinomas and B16 melanomas by modulating the function of macrophages in the tumor, resulting in increased longevity." (PMID 39857239, 2024). "The results found that the expression levels of ABCG1, HAVCR2, CD14, and TGFA were significantly increased (p < 0.05) in tumor tissue samples compared with para-cancerous control tissue samples, while the expression levels of KDF1 and KITLG were significantly decreased (p < 0.05)." (PMID 35774505, 2022). "Importantly, tumor cholesterol efflux genes such as ABCA1, ABCG1 and the master regulator LXRs were also induced by XY018 treatment." (PMID 35804882, 2022). "We further isolated Sca-1+Abcg1+ cells from Gprc5a−/− mouse lungs that had not developed tumors and proved the capacities of these cells for self-renewal and tumor initiation." (PMID 32157214, 2020). "We further illustrated that the Sca-1+/Abcg1+ subset isolated from Gprc5a-KO mice that had not yet developed tumors showed self-renewal and tumor initiation capabilities." (PMID 32157214, 2020). "In conclusion, Apo A1 has several roles on different aspects of tumor progression and might inhibit tumor growth by downstream ABCA1/ABCG1 activation." (PMID 31598156, 2019).
tumor (continued). "The lower numbers of MDSCs in animals with myeloid ablation of ABCA1 and ABCG1 was specific to the tumor compartment as these cells were not decreased in the spleen of receptor knock-out mice relative to WT animals." (PMID 29069761, 2017). "Abcg1−M/−M (G1−M/−M) animals were also protected by 2.5-fold relative to WT, with no further inhibition of tumor growth in Abca1/Abcg1 myeloid-specific double knockout animals (DKO)." (PMID 29069761, 2017). "Both global and myeloid deletion of Abcg1 led to increased tumor immunity in young tumor bearing animals when fed a “western”-type diet, but not a normal chow diet." (PMID 29069761, 2017). "In contrast, another group cultured LNCaP xenografts in castrated mice, finding that ABCA1 and SR-BI expression was increased in the castration-resistant tumours, but ABCG1 expression was not investigated." (PMID 23320115, 2013). "Importantly, treatment with GW3965, alone or in combination, consistently induced the expression of the LXR target genes ABCG1 and SREBP1c, independent of the effect on tumor growth." (PMID 37341140, 2023). "Human tumor transcriptomic data for 377 HCC patients also show a positive correlation of multiple ABC transporters including the ABCB1, ABCC3, ABCC9 and ABCG2 with GHR expression, while ABCC1,ABCC4 and ABCG1 levels correlated with IGF1R expression, confirming our in vivo observations." (PMID 35865483, 2022). "However, roles for ABCG1 in tumor progression have not been completely clarified yet and require further study." (PMID 30364132, 2018). "Importantly, loss of myeloid Abca1 alone was sufficient to significantly inhibit tumor development (p=0.01), and additional deletion of Abcg1 in the same immune cells did not lead to enhanced suppression of tumor growth." (PMID 29069761, 2017). "In a luminal‐like model (MAS98.06), treatment with GW3965 did not inhibit tumor growth, but influenced the expression of the LXR target genes ABCG1 and SREBP1c." (PMID 37341140, 2023).
cancer (41 papers, 2010 to 2025). A tumor composed of atypical neoplastic, often pleomorphic cells that invade other tissues. "Our results showed significant upregulation in ABCB1, which is also known as multidrug resistance 1 (MDR1), ABCC6, and ABCG1, which were associated with cancer chemoresistance previously." (PMID 30832318, 2019). "Actually, the expression of ABCG1 is also associated with cancer stem cells (CSCs)." (PMID 38896016, 2024). "High expression of ABCG1 is usually associated with poor prognosis, which means ABCG1 may be a potential biomarker for early diagnosis and prognosis of various cancers." (PMID 38896016, 2024). "Thus, the decrease of cellular cholesterol concentration induced by ABCG1 is associated with cancer cell death." (PMID 38896016, 2024). "In addition, ABCG1 may be a potential target binding to some molecules of signal pathways including Hedgehog‐GLI, and the increased ABCG1 is linked to the enhanced chemoresistance in cancer cells." (PMID 38896016, 2024). "Targeted silencing of ABCG1 resulted in the accumulation of EV lipid and triggered cell death in tumors, suggesting that cancer cells can often release redundant toxic lipid, whereas loss of the ABCG1 pump could trigger the accumulation of redundant, toxic lipids." (PMID 31533245, 2019). "Protein expression levels of ABCG1 in a pan-cancer context were examined using the UALCAN cancer database, disclosing that ABCG1 levels in ccRCC (n = 110) were significantly higher compared to those in normal tissues (n = 84)." (PMID 40520894, 2025). "Our findings revealed that ABCG1 expression was elevated in the majority of cancer tissues, including ccRCC, in comparison to paracancerous tissues." (PMID 40520894, 2025). "ABCG1 supports cancer stem-like cells (CSCs) in osteosarcoma and Ewing sarcoma, enhancing cholesterol efflux to sustain CSC viability and multidrug resistance." (PMID 40370434, 2025). "Above all, ABCG1 functions in diverse signal modulation actions in different cancers, and usually acts as a pro‐tumorigenic role." (PMID 38896016, 2024). "Apart from the efflux role, ABCG1 is also confirmed to participate in several signaling pathways to enhance cancer cell chemoresistance." (PMID 38896016, 2024). "For the first time, we demonstrate that ABCG1, a potential oncogene in some cancers, is highly expressed in ES-CSCs independently of CD133." (PMID 36765727, 2023). "All of our data suggest that ECM1a plays a tumorigenic role and confers cancer cell cisplatin resistance through integrin αXβ2/hnRNPLL/ABCG1-mediated cellular phosphorylation signaling and stemness induction." (PMID 34244494, 2021). "Additional putative targets of miR-129-5p that are associated with drug resistance in cancers are ABC transporters (ABCB1, ABCC5, ABCG1) and RUNX1." (PMID 34063443, 2021). "A recent study proves that the Sca-1+Abcg1+ bronchioalveolar epithelial cells are the cancer stem cell-like subset of AT2 cells and are the origin of LADC in GPRC5A-knockout mice." (PMID 32771979, 2020). "In the present study, we showed that ABCG1 is crucial in regulating the CSC-like property of AT2, highlighting the important role of ABCG1 in cancer initiation." (PMID 32157214, 2020). "Several ABC transporters, including ABCG1, are associated with multidrug resistance (MDR), which is a major obstacle to the effective clinical treatment of cancer." (PMID 31931755, 2020). "The RNA levels of Abcb1a, Abcg1 and Abcg2, some of the most studied drug transporters in cancer, were elevated in bGH and GHRKO mice, both of which have elevated circulating GH irrespective of the levels of IGF-1." (PMID 33291663, 2020). "We demonstrated that depletion of ABCG1 triggered the intracellular accumulation of EV-lipid and reduction of the cancer cell viability." (PMID 30364132, 2018).
cancer (continued). "Our current study includes assessment of select ABC superfamily gene members (including ABCB1, ABCC1, ABCC2 and ABCG1) known to act as active drug transporters to reduce accumulation of chemotherapy drugs within resistant cancer cells." (PMID 30477242, 2018). "We showed that depletion of ABCG1 increased the accumulation of EVs, lipoproteins, and their potential cargos in the metastatic cancer tumoroids leading to reduction in their viability." (PMID 30364132, 2018). "Recent studies showed that ABCG1 was crucial for cancer-initiating/stem cell (CIC/CSC) survival of gliomas." (PMID 30364132, 2018). "ABCA1 and ABCG1 exhibit context-specific roles in pediatric cancers." (PMID 40370434, 2025). "In addition, it was reported that ABCG1 depletion suppressed the release of extracellular vesicles from cancer cells, inducing lipid accumulation and inhibiting cancer cell proliferation." (PMID 40362545, 2025). "ABCG1 functions actively in diverse tumors, and may facilitate cancer cell growth through mediating the phosphorylation of cellular signaling molecules." (PMID 38896016, 2024). "The upregulated expression of ABCG1 is potential to kill cancer cells." (PMID 38896016, 2024). "Actually, the lipids efflux induced by ABCG1/EVs is also critical for the viability of cancer cells because the levels of both are largely increased and the depletion of ABCG1 leads to the accumulation of EVs containing lipids in cancer cells." (PMID 38896016, 2024). "In addition to signaling pathway, ABCG1 is also detected to support the growth of cancer stem cells through suppressing ER stress." (PMID 38896016, 2024). "The interest in the role of ABCG1 in cancer has increased in recent years." (PMID 39857239, 2024). "So far, ABCG1 has been confirmed to be involved in cholesterol efflux and links to some metabolic diseases, yet less is mentioned about the relationship between ABCG1 and cancer growth." (PMID 38896016, 2024). "Since chemoresistance is associated with cancer cell stemness, we tested some stem cell transcription factors and found that Oct4A was particularly upregulated by ABCG1 overexpression, whereas c-Myc and SOX2 were upregulated by both ECM1a and ABCG1." (PMID 34244494, 2021). "A few studies have indicated that ABCG1 is also connected with human cancer." (PMID 32157214, 2020). "Interestingly, PPIs also have a pro-apoptotic effect to cancer cells, implicating a potential accumulation mechanism similar with ABCG1-depletion." (PMID 30364132, 2018). "We then showed that depletion of the ABCG1 pump triggers the accumulation of autocrine EVs that could trigger regression of malignant tumors." (PMID 30364132, 2018). "The detailed mechanisms in chemoresistance induced by ABCG1 is still not very clear, but this may be associated with the level of cholesterol‐induced cancer cell viability." (PMID 38896016, 2024). "ABCG1‐targeted therapy may provide a novel treatment for cancer patients." (PMID 38896016, 2024). "In addition to cholesterol efflux, ABCG1 may induce chemoresistance and improve cancer cell viability by an independent efflux mechanism, which may be more related to ABCG1 expression in nucleus rather than cytoplasm." (PMID 38896016, 2024). "Thus, ABCG1 may confer cell stemness and maintain stem‐like properties by enhancing aerobic glycolysis of malignant tumors through the HIF‐1a/PDK1 signaling axis." (PMID 38896016, 2024). "ABCG1 may prevent cancer cell from accumulation of cytotoxic lipids through extracellular vesicles." (PMID 38896016, 2024). "Thus, we focused on the stemness of cancer cells induced by ABCG1." (PMID 34244494, 2021). "Therefore, targeting ABCG1 may enhance chemotherapeutic efficacy for cancers, especially those with ECM1a/ABCG1 activation." (PMID 34244494, 2021).
cancer (continued). "This evidence, taken together with the observation that alterations in the ABCG1 gene were observed in 40% of invasive breast cancer tumors in the Cancer Genome Atlas, provides a potential epigenetic link between MetS and chronic diseases including cancer that deserves further study." (PMID 29643945, 2018). "Emerging data suggests that cancer cells secrete factors that activate cholesterol transporters in macrophages such as ABCA1 ABCA6 and ABCG1 to increase cholesterol efflux." (PMID 37872251, 2024). "ABCG1 downregulated miR-29a, miR-29b and miR-29c expression in HKULC4 cells and promoted migration and invasion of cancer cells." (PMID 34281263, 2021). "Our results showed that U87MG cells acquired resistance to 5-FU through its conversion to cancer stem cells along with upregulation of mdm2 oncogene and ABC transporter genes, ABCB1 and ABCG1." (PMID 24391839, 2013). "An increase in CD24high/CD44low cancer stem cells and upregulation of key ABC transporter genes (ABCG1 and ABCB1) imparted resistance to 5-FU in U87-MCSF cells." (PMID 24391839, 2013). "We further demonstrated that HOXB2 modulated the expression of long non-coding RNA DANCR, a differentiation antagonizing non-protein coding RNA, and thus influenced its downstream effectors ABCA1, ABCG1, and ERK signaling to boost drug resistance and cancer proliferation." (PMID 38851728, 2024). "Consistent with our studies, ERK1 and 2 are linked to regulation of many ABC genes, including ABCG1, ABCA1, MDR1, and MRP1 in various cancer and non-cancer cells." (PMID 21159167, 2010). "The ATP binding cassette subfamily G member 1 (ABCG1) transduces the ECM1a-integrin αXβ2 interactive signaling to facilitate the phosphorylation of AKT/FAK/Rho/cytoskeletal molecules and to confer cancer cell cisplatin resistance through up-regulation of the CD326-mediated cell stemness." (PMID 34244494, 2021). "The higher methylation levels of ABCG1 observed with MetS provide evidence for potential therapeutic targets that may be useful in drug development, and/or prevention of chronic diseases including CVD and cancer." (PMID 29643945, 2018). "Consistent with the in vivo evidence that fasting stimulates ABCG1, but not ABCA1 expression, we observed that in vitro, cholesterol efflux from both HCT116 and MCF7 cancer cells only increased under FMCC when HDLs, but not ApoA-I were used as acceptors." (PMID 37907500, 2023).
cardiovascular disease (12 papers, 2013 to 2025). "Inhibition of ABCG1 results in intracellular cholesterol accumulation, demonstrating the critical role of ABCG1‐dependent cholesterol transport in lipid homeostasis and in stifling the progression of cardiovascular disease." (PMID 39804798, 2025). "The ABCG1 gene encodes the ABCG1 protein that is essential for the regulation of lipid metabolism and influences blood lipid levels, and the APOE gene is considered a candidate gene for cardiovascular disease because the APOE protein influences total serum cholesterol levels in different ways." (PMID 31823830, 2019). "High-density lipoprotein (HDL) cholesterol, protective against cardiovascular disease, facilitates reverse cholesterol transport via ABC transporters ABCA1 and ABCG1." (PMID 41416067, 2025). "Epigenetic modification of ABCG1 and APOE may play a key role in the pathway from disturbed blood lipid levels to the development of cardiovascular diseases." (PMID 31823830, 2019). "At present, clinical staff shows a strong interest in ligands for LXRS and PPARs for the treatment of cardiovascular disease, and they are ligand-activated transcription factors that plays well-established roles in up-regulating transcription of ABCA1 and ABCG1." (PMID 24314261, 2013).